ALK (ALK receptor tyrosine kinase)
Diseases named in the same sentence as ALK in open-access papers (continued):
Sharing a sentence is not in itself a finding about the gene and the disease.
lung cancer (continued). "In oligoprogressive diseases of ALK+ lung cancer, continuation of ALK TKIs with local ablative therapy should be considered for sustained control, which can potentially eradicate resistant cancer cell clones and confer survival benefit." (PMID 35463328, 2022). "Another study looks at the efficacy and safety of alectinib in participants with anaplastic lymphoma kinase (ALK)-positive locally advanced or metastatic solid tumors other than lung cancer (ALpha-T or NCT04644315)." (PMID 36291857, 2022). "Previous studies have shown that PD-L1 TPS ≥50% in lung cancer rarely overlaps with driver oncogenes such as epidermal growth factor receptor and anaplastic lymphoma kinase (ALK)." (PMID 35984185, 2022). "Crizotinib was approved to treat advanced NSCLC with rearranged anaplastic lymphoma kinase (ALK) or ROS1 gene, and dabrafenib which targets a rare mutation in lung cancer (BRAF V600E) was approved for the treatment of BRAF-positive advanced NSCLC." (PMID 35061839, 2022). "Studies have shown that the ALK oncoprotein is able to upregulate PD-L1 expression in lung cancer cells." (PMID 35463328, 2022). "Non–small cell lung cancer with an ALK fusion and high PD-L1 expression responds poorly to most current treatment options, with survival time after ALK-tyrosine kinase inhibitor treatment notably shorter than that of patients with an ALK fusion alone." (PMID 35984185, 2022). "Anaplastic lymphoma kinase (ALK) tyrosine kinase receptor has been identified as a therapeutic target in lung cancer." (PMID 36591504, 2022). "Treatment with these second-generation ALK inhibitors has been well tolerated and has shown efficacy in crizotinib-resistant lung cancers with ALK rearrangement." (PMID 35366157, 2022). "Sarcoidosis and ALK-positive NSCLC are uncommon together, and ALK-positive lung cancer is likely to spread rapidly." (PMID 35103216, 2022). "There were 103 (1.37%) cases harboring ALK rearrangements in 7,537 solid tumor patients, including lung cancer (n=93), soft tissue sarcoma (n=6), bone tumor (n=1), esophagus cancer (n=1) and other unspecified tumors (n=2)." (PMID 35785159, 2022). "The common drivers of lung cancer, such as EGFR mutations and ALK rearrangement, are rarely detected in pLELC, indicating that the key carcinogens of LELC are not tobacco exposure or somatic cell driver mutations." (PMID 35237520, 2022). "As the most common fusion type of ALK, EML4-ALK is responsible for the growth and survival of lung cancer cell lines and functions as a therapeutic target in NSCLC." (PMID 36523965, 2022). "Although they rarely occur in lung cancer, KRAS mutations combined with EGFR mutations or ALK rearrangement predict poorer response to tyrosine kinase inhibitors (TKIs)." (PMID 36077640, 2022). "Here, we report the case of a patient who had ALK-positive locally advanced lung cancer with multiple lymph node metastases and was successfully treated with salvage surgery between the ALK–TKI sequential therapy." (PMID 35366157, 2022). "This is particularly urgent in lung cancer, where mutations in EGFR, ALK, ROS, RET, METex14 skipping, BRAF, and KRAS should be identified before initial treatment." (PMID 35862868, 2022). "All ALK fusions took place at the 5’ end of the protein and breakpoints in intron 19 were highly recurrent, accounting for 95% overall, 96% in lung cancers and 81% in non-lung cancers, producing fusion products fused to exon 20 of the ALK gene." (PMID 36369474, 2022). "Here, we investigated the molecular mechanisms underlying the emergence and maintenance of drug-tolerant cells in ALK-rearranged lung cancer." (PMID 35042943, 2022). "More recently, following the results of the phase 3 trial—ALK in lung cancer trial of brigatinib in 1st line (ALTA-1L)—brigatinib was granted marketing authorization for the first-line treatment of advanced ALK+ NSCLCs." (PMID 35406523, 2022).
lung cancer (continued). "The characteristics of second lung cancer were strikingly similar: 100% were ER-negative, 95% had wild-type ALK, and 85% exhibited low Ki67 (<30%)." (PMID 36313724, 2022). "Alternatively, BCL-XL overexpression using a lentiviral expression vector significantly decreased apoptosis induction in ALK-rearranged lung cancer cells treated with alectinib and YHO-1701." (PMID 35228642, 2022). "For example, epidermal growth factor receptor (EGFR)-tyrosine kinase inhibitors (TKIs) and anaplastic lymphoma kinase (ALK)/c-ros oncogene 1 (ROS1) inhibitors have replaced chemotherapy as the first-line treatment of lung cancer." (PMID 36559280, 2022). "The efficacy of ceritinib was confirmed in patients with ALK-rearranged lung cancer, including patients with brain metastases who progressed on chemotherapy and crizotinib." (PMID 36523965, 2022). "Lung cancers that are ALK gene rearrangement-positive can be effectively treated with ALK inhibitors." (PMID 35280798, 2022). "The occurrence of isolated CNS relapse, highlights the need for new TKI sequence studies to optimize the management of ALK‐translocated lung cancer." (PMID 35092185, 2022). "Here, we developed a GEM model specifically for EML4‐ALK lung cancer and found that XMU‐MP‐5 led to strong tumor regression resulting from ALK activity inhibition and tumor cell apoptosis." (PMID 34845836, 2022). "Since the discovery 15 years ago, we have seen a quantum leap in the treatment and survival for individuals diagnosed with ALK+ lung cancers." (PMID 36003760, 2022). "ALK inhibition is the first-line therapy for lung cancers with ALK alterations, and an effective therapy in other tumor types, but has not been well-studied in prostate cancer." (PMID 36337169, 2022). "Zhou used camrelizumab and apatinib to treat patients with advanced EGFR and ALK wild-type non–small cell lung cancer; he found that the combination regimen significantly reduced reactive capillarity to 15.6%—a rate similar to that in our study." (PMID 35280787, 2022). "Since then, new medications (for example, crizotinib for ALK-positive lung cancer) have been developed in reverse by first investigating disease biology to identify genetic lesions in lung cancer, and then designing a therapy to target those lesions." (PMID 35454856, 2022). "Functional genomic screening using small guide RNA libraries showed that treatment-induced adaptive survival of ALK-rearranged lung cancer cells was predominantly dependent on STAT3 activity upon ALK inhibition." (PMID 35228642, 2022). "ALK plays an important role in the occurrence and metastasis of non–small cell lung cancer, malignant peritoneal mesothelioma, gynecologic clear cell carcinoma, melanoma, etc.." (PMID 36128740, 2022). "In our study, TOPK was phosphorylated on tyrosine residue Y74 by ALK and promoted tumor growth of ALK-positive lung cancer cells." (PMID 36167821, 2022). "Overall, our results indicate that the treatment-induced adaptive survival of ALK-rearranged lung cancer cells is predominantly dependent on STAT3 activity." (PMID 35228642, 2022). "STAT3 inhibition effectively suppressed the adaptive survival of ALK-rearranged lung cancer cells by enhancing ALK inhibition-induced apoptosis." (PMID 35228642, 2022). "Given the proven efficacy of ALK inhibitors in non–small cell lung cancers, their clinical utility has been tested across a broad spectrum of tumor types." (PMID 36337169, 2022). "The fusion of ALK with echinoderm microtubule-associated protein like-4 (EML4) gene creates the fusion gene EML4-ALK, which is the most observed ALK fusion in lung cancer." (PMID 36230484, 2022). "It has been reported that patients with ALK-positive lung cancer are four times more likely to have VTE than patients with other types of lung cancer." (PMID 36089919, 2022). "ALK fusions in non-lung cancer patients were more commonly fused with non-EML4 partners (Bonferroni’s post-test, P < 0.0001)." (PMID 36369474, 2022).
lung cancer (continued). "The optimal sequence of TKI in ALK‐positive lung cancer and the role of surgery and radiotherapy at CNS dissemination remain critical." (PMID 35092185, 2022). "The ALK in Lung Cancer Trial of brigAtinib in First Line (ALTA‐1L) compared brigatinib versus crizotinib in anaplastic lymphoma kinase (ALK) inhibitor‐naive patients with ALK+ non‐small cell lung cancer (NSCLC)." (PMID 35041775, 2022). "For example, trastuzumab is used for HER2-amplified breast cancer BrM, tragisso (Osimertinib) for EGFR-mutant lung cancer BrM, and xalkori (Crizotinib), alecensa (Alectinib), alunbrig (Brigatinib), and zykadia (Ceritinib) against ALK-rearranged BrM." (PMID 35225863, 2022). "We next validated the in vitro findings in vivo using cell line-derived xenograft model of ALK-rearranged lung cancer." (PMID 35228642, 2022). "Anaplastic lymphoma kinase (ALK) gene rearrangements that lead to constitutive activation of the ALK kinase are observed in approximately 5% of non–small-cell lung cancer (NSCLC)." (PMID 35565470, 2022). "Such an approach to care will require a complete paradigm shift in the way we approach the treatment of advanced cancer, however evidence to date in ALK+ lung cancers, support this new frontier of investigation." (PMID 36003760, 2022). "Certainly, treatment of ALK rearranged lung cancer patients with oligoprogressive disease must be individualized and based on multidisciplinary decisions." (PMID 35158987, 2022). "Targeted drugs against KRAS-, EGFR- or ALK-driven lung cancer induce apoptosis and pyroptosis simultaneously." (PMID 36411454, 2022). "More recently, molecular markers were added, EFGR and ALK alteration have been used as a factor for grading lung cancer patients with brain metastasis (Lung-molGPA)." (PMID 36135077, 2022). "Results of a randomized, multicenter phase II trial (ALK in Lung Cancer Trial of AP26113 [ALTA], NCT02094573) supported the initial approval of brigatinib in advanced ALK‐positive (ALK+) NSCLC that progressed on crizotinib." (PMID 35041775, 2022). "Despite impressive and durable responses, nonsmall cell lung cancer patients treated with ALK inhibitors (ALK‐Is) ultimately progress due to the development of resistance mechanisms." (PMID 34058070, 2021). "The molecular testing of lung cancer usually screens for genes encoding epidermal growth factor receptor (EGFR), anaplastic lymphoma kinase (ALK) and Kirsten rat sarcoma viral oncogene homolog (KRAS)." (PMID 33747933, 2021). "Lung cancer is often driven by molecular alterations, such as EGFR and KRAS mutations, and ALK rearrangements expressed in tumor tissues of patients with NSCLC." (PMID 34722241, 2021). "The ALEX phase 3 clinical trial included previously untreated patients with advanced ALK-positive lung cancer." (PMID 33435596, 2021). "ALKIs have been shown to be superior to traditional cytotoxic chemotherapy in ORR, OS, and PFS for treatment-naïve ALK-positive lung cancer patients in several trials." (PMID 33921762, 2021). "At present, five different ALK‐Tyrosine kinase inhibitors (ALK‐TKIs) have been approved by food and drug administration (FDA) to treat ALK‐positive non‐small cell lung cancer (NSCLC) patients." (PMID 34766150, 2021). "ALK-positive (anaplastic lymphoma kinase positive, or ALK+) lung cancer occurs in 1 out of 25 non-small-cell lung cancer patients." (PMID 33467741, 2021). "Anaplastic lymphoma kinase (ALK) rearrangement is the second most common targetable oncogene-dirven gene in nonsmall cell lung cancer." (PMID 34941039, 2021). "Therapies that target driver gene mutations (e.g. EGFR, ALK, ROS1) and checkpoint inhibitors such anti-PD-1 and PD-L1 immunotherapies are being used to treat lung cancer patients." (PMID 33956842, 2021). "Currently, several different techniques can be used to identify ALK-rearranged lung cancers, such as immunohistochemistry and fluorescence in situ hybridization." (PMID 33738250, 2021).
lung cancer (continued). "Future directions: genetic drivers of brain metastases.—Driver alterations such as those occurring in EGFR and ALK are responsible for tumorigenesis and therefore represent early, seminal genetic events in lung cancer development." (PMID 34859233, 2021). "In order to understand the efficacy and AEs of these new-generation ALKIs, several meta-analyses have been performed to identify the most beneficial ALKIs for ALK-positive lung cancer patients." (PMID 33921762, 2021). "Currently, alectinib and crizotinib are considered effective in the treatment of ALK-positive lung cancer." (PMID 34591871, 2021). "In lung cancer, the MAPK pathway is driven by oncogenic mutations (e.g., BRAF and RAS mutations), RET-PTC, and in some cases by the recently discovered ALK mutations." (PMID 33628588, 2021). "In the present study, we sought to implement the NanoString panel of ALK fusion detection for lung cancer patients, our NanoString results were further compared with immunohistochemistry or FISH analysis of ALK and showed a full concordance of methodologies." (PMID 34234236, 2021). "Some studies have shown that in ALK rearranged lung cancer patients, the proportion of advanced tumors and early lymph node metastasis is higher." (PMID 34596344, 2021). "Lung cancers with anaplastic lymphoma kinase (ALK) rearrangements are highly sensitive to treatment with ALK tyrosine kinase inhibitors (TKIs)." (PMID 34324792, 2021). "Based on these results, the United States (US) National Comprehensive Cancer Network (NCCN) guidelines and the Japanese lung cancer practice guidelines recommend alectinib as the first-line treatment for ALK-p advanced NSCLC." (PMID 34359604, 2021). "EML4-ALK translocation results in constitutive ALK tyrosine kinase activity, representing an oncogenic addiction pathway in lung cancer." (PMID 33806977, 2021). "Small molecular inhibitors, effecting on KRAS, EGFR, ALK in lung cancer 11, BRAF and MEK in melanoma cells 63, elicit concurrent GSDME-mediated PCD." (PMID 34335940, 2021). "Treatment of advanced lung cancer has dramatically changed since the discovery of the EGFR gene mutation in the 2000s and various driver gene mutations, including ALK rearrangement." (PMID 33963234, 2021). "Nevertheless, grade 3–4 adverse events are observed in response to alectinib in ALK-rearranged lung cancer." (PMID 34591871, 2021). "Features of EMT were simultaneously found with ALK resistance mutations in a single tumor of a patient with ALK-rearranged lung cancer, who had developed resistance to ALK-TKI treatment." (PMID 33572278, 2021). "As NSCLC accounts for more than 84% of all lung cancers, the treatment of ALK-p NSCLC with CNS metastases is becoming increasingly important as advances in lung cancer treatment ensure prolonged survival." (PMID 34359604, 2021). "Anaplastic lymphoma kinase (ALK) inhibitors have been approved for patients with ALK-rearrangement lung cancer." (PMID 34190169, 2021). "Excitingly, our finding revealed a dramatical increase of SPP1 mRNA (35.954-fold) in ALK-positive lung cancers using NanoString analysis and then overexpression of SPP1 protein was confirmed by IHC." (PMID 34234236, 2021). "A study on 110 patients evaluated if MR radiomics from brain metastasis originated from lung cancer was shown to associate with EGFR, ALK and KRAS mutations and reported excellent model performances for all three tissue biomarkers (AUC > 0.9, LOOCV)." (PMID 34208595, 2021). "HER2 plays an important role in regulating cancer stem cell phenotypes of ALK translocation lung cancer, which is primarily mediated by HER2/HER3 heterodimers." (PMID 34660278, 2021). "Analysis of the expression levels of common immune checkpoints (PD1 and PD‐L1 in our study) and lung cancer driver genes (ALK, EGFR, ROS1, and MET in our study) between two clusters revealed significant differences in PD1, PD‐L1, and MET gene expression." (PMID 34558724, 2021).
lung cancer (continued). "Our study demonstrated that abnormally high levels of SPP1 were present in patients with ALK-positive lung cancers, similar to previous findings in pediatric patients with ALK-positive anaplastic large cell." (PMID 34234236, 2021). "Echinoderm microtubule-associated protein-like 4 – anaplastic lymphoma kinase (EML4-ALK) gene fusions are prevalent in lung cancer and treatment with ALK inhibitors is a part of conventional care." (PMID 33878728, 2021). "A LB at diagnosis in late stage lung cancer has been developed using mostly targeted sequencing, notably for the detection of EGFR mutations or ALK/ROS1 fusions." (PMID 33922637, 2021). "Anaplastic lymphoma kinase (ALK) fusion is a well‐defined biomarker for ALK tyrosine kinase inhibitors (TKIs) treatment in non‐small cell lung cancer (NSCLC)." (PMID 34541785, 2021). "We believe this study provides reliable and feasible information to help physicians and ALK-positive lung cancer patients when making treatment decisions." (PMID 33921762, 2021). "For instance, we have only one patient tumour out of 851 lung cancer patients that exhibited ALK rearrangement (0.12%), while other studies report a frequency of 3 to 6%." (PMID 33956842, 2021). "Adenocarcinomas in non-smokers have some distinctive features arising from gene alterations, including a lower mutational load compared to other lung cancer histologies and oncogenic factors such as EGFR mutations or rearrangements of the ALK or ROS1 genes." (PMID 34857781, 2021). "The genetic alterations of ALK are found in various hematologic and stromal malignancies, including lymphomas, lung cancer, neuroblastoma, rhabdomyosarcoma, renal cell carcinoma, inflammatory IMT, inflammatory breast cancer, and melanoma." (PMID 37206935, 2021). "Inhibitors specific for ALK reportedly suppress the growth and induce apoptosis of lung cancer cells." (PMID 34090412, 2021). "LC3-independent canonical autophagy has previously been described in conditions of amino acid starvation or ER stress in prostate cancer cells, and very recently also in lung cancer cells treated with ALK inhibitors." (PMID 34943939, 2021). "A good illustration is epidermal growth factor receptor (EGFR)/anaplastic lymphoma kinase (ALK) in lung cancer, CD19 in diffuse large B cell lymphoma and HER2 in breast cancer." (PMID 34872521, 2021). "The discovery of EGFR, ALK and other driving genes in lung cancer provides an example for targeted therapy of malignant tumors." (PMID 33585082, 2021). "Nevertheless, for screening and diagnostics, also IHC is commonly used to detect ALK protein expression due to its very high sensitivity and specificity in identifying ALK positive lung cancers in concordance with FISH results." (PMID 34206978, 2021). "We focused on the association between cytomorphologic features, such as SRC components, extracellular mucin, cribriform pattern, and ALK- positive lung cancer." (PMID 34530849, 2021). "Anaplastic lymphoma kinase (ALK) rearrangement is a well-known driver oncogene in non–small-cell lung cancer and has also been identified in other types of tumors." (PMID 34036223, 2021). "One such panel is the Ion Ampliseq RNA fusion lung cancer panel offered by ThermoFisher Scientific, Waltham, USA, which targets 70 known fusion transcripts of ALK, RET, ROS1, and NTRK." (PMID 34571741, 2021). "ALK-rearranged lung cancer can be identified by immunohistochemistry (IHC), FISH or qRT-PCR with each method having advantages and disadvantages for screening." (PMID 33946969, 2021). "Anaplastic lymphoma kinase (ALK) inhibitors (ALK‐Is) have dramatically improved outcomes of nonsmall cell lung cancer (NSCLC) patients whose tumors harbor an ALK translocation." (PMID 34058070, 2021). "In conclusion, the clinical efficacy of ALK‐TKIs including alectinib for lung cancer with uncommon ALK gene fusions is still under evaluation." (PMID 34541785, 2021).